STAT3 (signal transducer and activator of transcription 3)
Diseases named in the same sentence as STAT3 in open-access papers (continued):
Sharing a sentence is not in itself a finding about the gene and the disease.
tumor (continued). "Furthermore, these effects were cell-type specific; Capz did not inhibit STAT3 phosphorylation in U266, A549, K562, or MDA-MB231 tumor cells." (PMID 27458171, 2017). "Overexpression of GRIM19 has therapeutic properties against cancer by inhibiting STAT3-mediated signal transduction, while the absence of GRIM19 abrogates mitochondrial respiratory chain function and accelerates tumor development by enhancing the expression of STAT3-responsive genes." (PMID 27391226, 2016). "The ERK activation status, on the other hand, did not correlate with proliferation in autochthonous tumours, xenografts, or cultured cells, implying that in the absence of RAF1 proliferative signalling is rewired to rely on the activation of YAP1 and STAT3 rather than ERK." (PMID 28000790, 2016). "However, neither STAT3 activation nor anti-tumor activity of IL-6 antibody CNTO328 was observed in our HCC4006ER cells, suggesting that the IL-6/STAT3 pathway is not necessarily activated in EMT-related acquired EGFR-TKI resistance in NSCLC." (PMID 26789630, 2016). "Thus, we wonder why cells choose to response to the suppressive effect of STAT1 rather than the activation effect of STAT3 in terms of SLUG expression, cell motility, and tumor metastasis, while OSM activates both." (PMID 27486982, 2016). "Mouse tumor epithelial cells do not express IL-21R, and stimulation of immortalized CRC cells derived from C57BL/6J mice with IL-21 does not affect cell growth and activation of STAT3/NF-kB." (PMID 25839161, 2015). "Our recent studies found that high expression of SOCS3 could reduce tumor metastasis, EMT markers and STAT3 activation in the absence of IL-6 stimulation in CCA cell lines." (PMID 26485275, 2015). "Our recent studies suggested that enhanced expression of SOCS3 could reduce tumor metastasis, the expression of epithelial-to-mesenchymal transition (EMT) markers and STAT3 activation in the absence of interleukin-6 (IL-6) stimulation in CCA cell lines." (PMID 26485275, 2015). "Some authors reported that Stat3-dependent S100A9 up-regulation enhances MDSC generation in vitro and that the immune system of mice lacking S100A9 have a greater ability to reject the tumor implant." (PMID 25538892, 2014). "Whether STAT3-mediated upregulation of STAT1 and CRP actually supports or suppresses tumor growth is not clear to this point despite both STAT1 and CRP potentially having both pro- and anti-tumor activity." (PMID 24743777, 2014). "PC3M-1E8 cells transduced with nontargeting shRNA control rapidly formed tumor, in contrast, PC3M-1E8 cells transduced with STAT3 shRNA displayed increased tumor latency and decreased tumor growth rate, concomitant with reduction of CSC marker expression in tumor." (PMID 25261365, 2014). "In the first example of supervised GSAA, we had demonstrated that the PDGFRB signal transduction pathway (PDGFRB_STP) was differentially regulated by STAT3 and MYC in non-tumor and tumor components, which was supported by our previous studies (and unpublished data of ours)." (PMID 23516564, 2013). "Both PKR and STAT3 affect normal cellular functions, such as cell proliferation, death and play an important role in cell transformation and tumors, PKR and STAT3 are both present in greater number in HCV-derived HCC tumor tissue than nontumor tissue." (PMID 22312393, 2010). "Importantly, in normal SVZ cells, chemically HIF-1α stabilization was only transiently inducing REDD1 upregulation and Akt/mTOR pathway was not inhibited, unlike in tumor cells, following BMP2 treatment, and Akt and Stat3 were eventually upregulated." (PMID 19587783, 2009). "Thus, its interesting to note that several genes thought to play a role in the processes of invasion, tumour progression and metastasis (MME, STAT3, DCBLD2, S100A10, CD9, S100A8) were highly downregulated in the NE vs the non-NE tumour group." (PMID 18827820, 2008).
tumor (continued). "In UVB-induced skin carcinogenesis, such redox modulation may reduce oxidative stress and attenuate downstream pro-inflammatory and pro-proliferative pathways, including IL-6/STAT3 and ERK/JNK, thereby preferentially affecting tumor promotion rather than UV photoproduct-driven initiation." (PMID 41596287, 2026). "Overall, while STAT3 inhibition did not significantly impact cell viability, proliferation, or CD44 induction after HER2 inhibition, JAK1 inhibition appeared to sensitize cells to HER2 inhibition and impair proliferation during the recovery phase in CD24+/CD44+ tumor cells." (PMID 40430044, 2025). "The targeting of STAT3, which is a player in TNBC proliferation and migration, may be another promising target in combination with immunotherapy, since it is dysregulated in both tumor and non-tumor cells in the tumor microenvironment." (PMID 39272915, 2024). "The therapeutic potential of remodeling the ECM by targeting STAT3 signaling has been reported in a study indicating that AZD1480 inhibitor, when combined with gemcitabine, enhances drug delivery in PDAC models by effectively remodeling the tumor stroma, without detrimental effect." (PMID 38124183, 2023). "NF-kB-induced IL-6 stimulates STAT3 activation in intestinal epithelial cells and promotes tumorigenesis in CAC through the inhibition of apoptosis and induction of cell proliferation, although IL-6 does not have significant effect on early tumor promotion in the CAC." (PMID 38273841, 2023). "These cytokines, secreted by cancer cells, immune cells, and other non-cancer cells within the tumor microenvironment, contribute to systemic inflammation and activate catabolic processes in muscle through transcriptional regulators such as p38 MAPK, nuclear factor kappa B (NF-κB), and STAT3." (PMID 35994202, 2022). "However, our observation of adjacent pSTAT3pos/IL-6neg and pSTAT3neg/IL-6pos foci in a HER2neg tumor, suggesting that there may not be an absolute (functional) correlation between HER2 expression and activation of STAT3 in transformed mammary epithelium." (PMID 35565421, 2022). "In addition, SHP-1 was found to inactivate signal transducers and activators of transcription 3 (STAT3) in HER2-overexpressing breast cancer cells (data not shown), thus indicating that the tumor-suppressive effects of SHP-1 cannot be fully compromised by EGFR/Ras/Erk/GSK3β pathway inactivation." (PMID 34591414, 2021). "Clathrin down‐regulation further significantly decreased AKT phosphorylation in response to AR, a ligand that is frequently produced at very high levels in the tumour environment of HCC, but increased STAT3 phosphorylation irrespective of whether cells were stimulated or not." (PMID 32515546, 2020). "The previously identified TFs—STAT1, STAT3, KDM1A, PML RELA, and TBL1XR1—did not exhibit a deviating correlation between the early and late tumor stages, indicating that their correlation remains constant throughout the different stages of the tumor compared to non-tumor tissues." (PMID 33384992, 2020). "However, the predicted activation of STAT3 rather than STAT1 in the upstream analysis using Ingenuity Pathway Analysis (IPA), suggests a possible negative regulation of IFNG/STAT1 signaling, counter-balancing the inflammatory anti-tumor response." (PMID 29100312, 2017). "While the nature of the activation signal(s) in this model is not known, the signaling pathways (ERK and STAT3) are the same as those observed in our studies of FGFR after treatment with AZD5363, indicating that in vivo it is possible for these pathways to maintain tumor proliferation." (PMID 28008155, 2017). "Together, these findings support our hypothesis that RIPK3 has anti-tumor properties and that lack of RIPK3 promotes the development of intestinal neoplasia through STAT3- and β-catenin-mediated transcription of angiogenic, mitogenic, tumorigenic and cell cycle regulators." (PMID 27344176, 2016).
tumor (continued). "Since, STAT3 is activated in oestrogen receptor (ER)-negative BCa36, we hypothesized that this transcription factor may be responsible for the transcriptional activation of PML in this tumour type." (PMID 27553708, 2016). "Treatment with SC-43 at 10 mg/kg/day did not significantly inhibit the tumor growth of STAT3-overexpressed MDA-MB-468 tumors and failed to suppress p-STAT3 expression in these tumors (right), indicating the pivotal role of downregulation of p-STAT3 in mediating the drug effects of SC-43." (PMID 23938089, 2013). "JSI-124 treatment confirmed the contact-dependency of STAT3 activation, as we have previously demonstrated that this JAK2 inhibitor selectively blocks contact-dependent STAT3 activation but not that induced by soluble factors, such as IL-10 or tumor cells conditioned media." (PMID 24073274, 2013). "However, therapeutic intervention could not reverse the tumor cell-induced STAT1 suppression (0.62±0.13) and STAT3 activation (2.65±1.07) in the lung tissues." (PMID 21931823, 2011). "However, studies on tumor immunity have also found that the knockout of STAT1 and STAT3 does not affect the constitutive expression of PD-L1, indicating a variety of cytokines may induce the expression of PD-L1 on tumor and/or immune cells through different signaling mechanisms." (PMID 38715061, 2024). "However, drug concentrations needed to achieve tumor growth inhibition in both ex vivo and in vivo assays were discordant with those necessary to achieve target inhibition in vitro, suggesting that the anti-tumor effects of LY5 are not due to inhibition of STAT3 phosphorylation." (PMID 28750090, 2017). "However, whether STAT3 overexpression in these tissues of patients with OS was purely restricted to the tumor compartment or was also a result of CAF contribution remains unclear, as coimmunolabeling for STAT3 and tumor- or fibroblast-specific cell phenotype markers was not performed in this study." (PMID 40099972, 2025).
cancer (6,946 papers, 2002 to 2026). A tumor composed of atypical neoplastic, often pleomorphic cells that invade other tissues. "To better understand how STAT3 mutations drive T-cell cancers, we compared two frequent cancer-associated variants, Y640F and N647I, at the cellular and molecular levels." (PMID 42164506, 2026). "For example, it is known that transient activation of JAK/STAT3-signaling is required to trigger cardioprotective effects of MSC-based therapies, but permanent elevation of STAT3 activity is associated with the formation of cancer." (PMID 41073800, 2026). "In SMAD4-deficient cancer cells, disruption of this interaction liberates NFATc1, enabling activation of oncogenic pathways such as STAT3 signaling." (PMID 40856537, 2026). "Although previous research has implicated STAT3 in the regulation of stemness and IL-17 signaling in cancer, the direct mechanistic connection between IL-17RA and STAT3-mediated CSC properties had not been demonstrated." (PMID 41438576, 2026). "Reduced OPN also diminished CD44 activation, impairing EMT-associated cancer stemness via JAK2/STAT3 and FAK/STAT3 pathways." (PMID 41356204, 2026). "For example, inflammatory signaling pathways such as nuclear factor kappa B (NF-kB) and signal transducer and activator of transcription 3 (STAT3) regulate genes linked to cancer progression." (PMID 41333220, 2025). "Hyperactivation of STAT3 is commonly observed in human cancers and is generally associated with unfavorable clinical prognosis." (PMID 40444012, 2025). "In the context of cancer, its action includes limiting the translation of pro-inflammatory senescence-associated secretory phenotype (SASP) factors (e.g. IL-1, STAT3, NF-κB), which reduces the risk of developing cancer in late life." (PMID 41497909, 2025). "In summary, we can conclude that MCPIP1 and IL6 are directly linked and that both MCPIP1 and the IL6/JAK2/STAT3 pathway play essential roles in many cancers." (PMID 40874680, 2025). "Deregulated STAT3 activation has been directly linked to many human cancers, highlighting it as a potential target for cancer therapy." (PMID 39786519, 2025). "Chronic exposure to this oxidative environment promotes the oncogenic mutations and activation of pro-cancer signaling pathways (e.g., NF-κB, or Signal Transducer and Activator of Transcription 3-STAT3)." (PMID 40723882, 2025). "In contrast, STAT3 has been linked to cancer cell survival, immunosuppression, and chronic inflammation in the TME." (PMID 40650089, 2025). "Accumulating evidence shows that STAT3 mutations participate in cancer pathogenesis, including in ENKTL." (PMID 40433378, 2025). "Previous study has also highlighted the oncogenic role of STAT3 in various cancers, where its constitutive activation is associated with poor prognosis and treatment resistance." (PMID 40697388, 2025). "At the molecular level, this phenomenon is intricately linked to TNF’s ability to activate STAT3-NF-κB signaling pathways, which enhance cancer cell growth and dissemination." (PMID 39980561, 2025). "A recent study showed that cancer-associated fibroblasts (CAFs) induce the differentiation of TANs into PD-L1+ neutrophils through the IL-6/STAT3/PD-L1 pathway." (PMID 40387965, 2025). "STAT3 plays a critical role in cancer development and abnormal activation is associated with several types of cancer, including brain, lung, pancreas, endometrium, colorectal, kidney, breast." (PMID 40535810, 2025). "Activation of STAT3 by tyrosine kinase inhibitors, a class of cancer therapeutics, has been associated with the development of resistance to these treatments." (PMID 40166646, 2025). "IL-22 has been associated via Stat3 activation with cancer-promoting properties in several types of cancer, including HCC, LC, and PC." (PMID 40806452, 2025). "Chronic inflammation can cause cancer by many pathway, such as nuclear factor-κB and STAT3 signaling." (PMID 40979720, 2025).
cancer (continued). "STAT3 is widely recognized as a proto-oncogene, and its constitutive activation is implicated in the pathogenesis of numerous cancers." (PMID 41476794, 2025). "The signal transducer and activator of transcription (STAT) family consists of six members, of which STAT3 has been the most implicated in cancer progression." (PMID 40075607, 2025). "Bazedoxifene has been identified as an effective inhibitor of the IL6/GP130/STAT3 pathway, which is implicated in the tumorigenesis and progression of these cancers." (PMID 40201234, 2025). "The expression levels of cancer stem cell-associated genes STAT3, SOX2, and MYC, varied among cancer cell clusters." (PMID 40883281, 2025). "STAT3 is highly implicated in the progression and survival of various cancers, establishing it as a key target in oncology." (PMID 40075607, 2025). "STAT3, implicated in cancer progression and chemoresistance, was similarly targeted by essential oil-based treatments in studies by Thalappil, Butturini, validating our results." (PMID 40284420, 2025). "CSF1R inhibition effectively depletes pathogenic macrophages in cGVHD, while STAT3/IDO modulation enhances monocyte‐derived dendritic cell activation for cancer immunotherapy." (PMID 40936181, 2025). "A pivotal player in this network is IL-6, which activates the potent pro-oncogenic JAK/STAT3 pathway, a process linked to the expansion of cancer stem cells and therapeutic resistance." (PMID 41302515, 2025). "The continuous activation of STAT3 is linked to the development of various cancers, including head and neck, breast, non-small cell lung, colorectal, and haematological malignancies." (PMID 40650089, 2025). "Stromal components, such as cancer-associated fibroblasts and tumour-associated macrophages, secrete IL-6 and activate the STAT3 and NF-κB pathways in cancer cells." (PMID 40806254, 2025). "HOXA10 has been implicated in the deregulation of multiple cancer types via activation of the JAK1/STAT3 signaling pathway." (PMID 40612864, 2025). "Activation of the STAT3 pathway in cancer-associated fibroblasts leads to elevated secretion of ANGPTL4, which is associated with shorter survival in patients." (PMID 39910592, 2025). "High-STAT3 activity is associated with poor prognosis in cancer; thus, STAT3 is an attractive target for drug development." (PMID 39792482, 2025). "STAT3 is a crucial transcription factor that mediates the expression of various genes associated with cancer stemness." (PMID 40696387, 2025). "Muscle wasting, a hallmark of cancer cachexia, is closely associated with aberrant activation of the STAT3 signaling pathway, which exerts multifaceted effects on muscle cell physiology and pathology." (PMID 40704145, 2025). "In more detail, STAT3 is involved in several signaling pathways underpinning cancer development and progression, and in many pathogenic pathways related to inflammation and cancerization." (PMID 41441207, 2025). "Abnormal expression of the STAT3 protein has been associated with various malignancies, particularly cancer." (PMID 40860906, 2025). "Through the modulation of NF‐κB, PI3K/Akt, and STAT3, as well as ROS‐mediated mitochondrial pathways, plumbagin causes apoptosis and cell cycle arrest, and inhibits metastasis in a variety of cancer types, including breast, prostate, and lung cancer." (PMID 40842665, 2025). "Specifically, prolonged inflammatory conditions in tumors are often linked to increased NF-κB activity and crosstalk with STAT3 signaling, thereby supporting cancer cell survival and proliferation." (PMID 40287766, 2025).